BRCA1 (BRCA1 DNA repair associated)
Diseases named in the same sentence as BRCA1 in open-access papers (continued):
Sharing a sentence is not in itself a finding about the gene and the disease.
tumor (continued). "Expression pattern analysis of the NOTCH1 gene indicated that TNBC and basal-type tumours exhibited significantly increased levels of NOTCH1, regardless of whether BRCA1 was mutated." (PMID 32591500, 2020). "Indeed, in MMR-deficient tumors but not in MMR-proficient tumors, frameshift mutations in mononucleotide tracts have been identified in tumor suppressors and DNA repair genes such as BRCA1, BRCA2 and BLM80,81, and tumor progression genes such as BAX82 and TGFB283." (PMID 33299637, 2020). "However, sequencing of BRCA1 and BRCA2 requires the analysis of a number of amplicons—too large to be added to a panel like ours—designed to cover relevant markers for the largest possible number of tumor types following the needs of our medical center." (PMID 32340363, 2020). "In contrast, overexpression of CISAL inhibited tumor growth and enhanced cisplatin sensitivity, whereas apoptotic tumor cells, CISAL, BRCA1, miR-593-5p, and MFF expression, were also detected, supporting the idea that enforced CISAL expression inhibits BRCA1 transcription in vivo." (PMID 32000125, 2020). "In another mice model bearing BRCA1-deficient ovarian tumors, anti-PD1 monotherapy exhibited a non-significant effect and PARPi monotherapy delayed tumor progression compared to control group, whereas combination therapy significantly slowed the tumor growth and prolonged survival time." (PMID 32526888, 2020). "The absence of BRCA1 nuclear expression correlates with high tumor grade and ER-negative tumors." (PMID 32235500, 2020). "Of the seven tumor samples without high frequent BRCA1/2 SNVs (P23-P25 and P30-P33) all but one case (P31) had heterozygous deletions of the complete BRCA1 and/or BRCA2 gene detected by CNV-calling." (PMID 31029168, 2019). "Similarly, PREDICT v1.3 performed well in Malaysian patients, but less accurately in patients with BRCA1 mutations, patients aged 40 years or less, and those with ER positive and HER2 negative tumours, and inconsistently in elderly patients." (PMID 30871490, 2019). "Indeed, in our series, one case showed a BRCA1/2 negative status in the primary tumor and a subsequent BRCA1/2 positive relapse." (PMID 31653094, 2019). "Thus, BRCA1 and BRCA2 are two genes that are crucial for repairing DNA damage and for ensuring genomic stability, preventing the accumulation of gross chromosomal rearrangements that would ultimately lead to either cellular apoptosis or tumor formation." (PMID 31130614, 2019). "In arm B, 74% of patients had unknown BRCA1/2 status (26% were BRCA1/2 negative); 49% and 51% had triple-negative and HR+ disease, respectively; and 40% had more than two tumor sites (liver metastasis, 60%)." (PMID 30240327, 2018). "In our BRCA2 –mutated xenograft, we did not observe an increased phosphorylation of ERK nor a decreased in BRCA1 gene expression after mTOR inhibition, indicating that this mechanism is not involved in the anti-tumor effect of olaparib and everolimus combination." (PMID 30038706, 2018). "Confirmatory studies of BRCA1 methylation zygosity in larger clinical cohorts will also be required; however, large PARPi trials in OC have focused on the maintenance setting, where tumor tissue immediately prior to PARPi has not been collected." (PMID 30266954, 2018). "Additionally, conditional knock-in mouse models were also used to investigate the role of Brca1 RING function in tumor suppression and therapeutic response, where it was determined that Brca1 RING did not affect resistance to therapy." (PMID 30079312, 2018). "Accordingly, methods established for routine germline BRCA1/2 testing may not be suitable for tumor testing as they are not optimized for highly fragmented DNA or to detect potentially low‐level somatic variants against a background of normal DNA." (PMID 29215764, 2018).
tumor (continued). "Estrogen activated the AKT pathway in BRCA1-deficient tumor cells independent of ER, and pharmaceutical inhibition of AKT activity suppressed EMT and cell proliferation preventing BRCA1 deficient tumor progression." (PMID 29996906, 2018). "The classification as benign seems appropriate for three variants: Gln356Arg affects estrogen receptor-dependent transcriptional repressor function; this function may not be important for the tumor-suppressor role of BRCA1." (PMID 29996917, 2018). "Indeed, ATM-associated tumours do not show the HRD signature characterised by large-scale state transitions, suggesting that tumorigenesis in BRCA1 variant carriers and ATM variant carriers occurs by different mechanisms." (PMID 29665859, 2018). "BRCA1-IRIS lacks key functional regions, such as the BRCT domains and protein-interacting regions, and its expression has been previously reported to promote growth factor-independent cell proliferation, anchorage-independent colony formation, and subcutaneous tumor xenograft growth." (PMID 29362392, 2018). "Among the 20 somatic-BRCA1/2-mutated tumor samples, there was one heterozygous BRCA2 mutation that lacked clear biallelic inactivation at the time of archival tumor collection prior to the Study 19 trial and two BRCA2 mutations predicted as subclonal somatic by the SGZ algorithm." (PMID 28525389, 2017). "Importantly, while PARP inhibitor treatment did not lead to a significant reduction in tumor weight inhibition (TWI), acetaldehyde inhibited the growth of allografts derived from Brca1−/−, 53BP1‐deficient cells by 54% (P < 0.001)." (PMID 28729482, 2017). "Continuous IHC nuclear score for BRCA1 correlated positively with CK5/6 (r = 0.24, p<0.0001), basal nature of the tumor (r = 0.52, p<0.0001), bcl2 (r = 0.13, p = 0.04), and AR nuclear (r = 0.33, p<0.0001) scores and negatively with age (r = -0.14, p = 0.048) and tumor grade (r = -0.25, p = 0.01)." (PMID 28863181, 2017). "Nevertheless, mutations in genes like BRCA1, BRAF, and PDGFBA were still detected in the plasma suggesting that tumor cells harboring these mutations were not eliminated by the therapy and that these mutations may actually confer a resistance mechanism." (PMID 28472989, 2017). "In the recent review the following definition has been proposed: “BRCAness is a phenocopy of BRCA1 or BRCA2 mutation; it describes the situation in which an homologous recombination repair defect exists in a tumour in the absence of a germline BRCA1 or BRCA2 mutation”." (PMID 27626685, 2016). "Some tumour cells displayed slight sensitivity to PARG deficiency, but this sensitivity could not be correlated to BRCA1- or PTEN-deficiency." (PMID 27375368, 2016). "Together, these data suggest that Ctip, unlike Brca1, is dispensable for tumor suppression in vivo." (PMID 27058754, 2016). "Similarly, in basal-like tumor forming cell lines, the CD44+/24–/low cells were enriched in BRCA1-defective HCC1937 (52.7 ± 1.84 %) when compared to HCC1937/wt BRCA1 (30.6 ± 5.0 %) that possesses a wild type BRCA1." (PMID 27229859, 2016). "Mice expressing this BRCA1 mutant display no increase in tumor formation, indicating that the ubiquitin ligase activity of BRCA1 may not be absolutely essential for its tumor suppressor function." (PMID 27446204, 2016). "Furthermore, it is a potential indicator of chemotherapy response since a lack of a functional BRCA1 gene results in an increased tumor cells' sensitivity to molecular damage." (PMID 27027444, 2016). "Both, BRCA1 and RRM2 mRNA levels were significantly higher in HGG (WHO grade III+IV) compared with LGG (WHO grade II), whereas the RRM2 expression was also significantly higher in WHO grade IV tumours compared with WHO grade III, thereby supporting our findings above." (PMID 27845331, 2016).
tumor (continued). "In a study including 50 male BRCA1/2 mutation carriers, it was suggested that BRCA2 MBCs may represent a subgroup of tumours with a peculiar phenotype not identified in FBC and characterised by an aggressive biological behaviour." (PMID 26857456, 2016). "Moreover, ionizing radiation (IR)-induced RAD51 foci assemble in olaparib-resistant Brca1−/−, 53BP1-deficient cells (albeit not at the same level as in Brca1+/+ cells), but not in olaparib-sensitive Brca1−/− tumor-derived cells." (PMID 26748828, 2016). "Interestingly, there was no significant relation between tumor grade and BRCA1 promoter methylation level." (PMID 27027444, 2016). "Thus, our results combined with those of others support the notion that BRCA1 LOH is not an obligatory early step in BRCA1-associated tumour progression and that BRCA1 LOH is likely to occur following the abrogation of other tumour-suppressive networks." (PMID 26106036, 2015). "Thus tumor genomic profile evidences intact functioning of BRCA1 and BRCA2 and no homologous recombination defect." (PMID 26426992, 2015). "The most significant (likelihood ratio test p = 0.0003) regression model included only covariates age (p = 0.030), a variable for the presence or absence of a germline BRCA1 or BRCA2 mutation (p = 0.062), and a log transformation of the total number of tumor mutations (p = 0.156)." (PMID 26215675, 2015). "Though, in a study that examined methylation status of six tumor suppressor genes that included BRCA1, BRCA2, p14, p16, hMLH, and MGMT in breast (n = 23), other tumor (n = 10), and control tissues (n = 4) suggested that BRCA1, BRCA2, and p14 appeared to be under strong epigenetic silencing." (PMID 25641872, 2015). "Although functional roles of BRCA1 may include the regulation of DNA damage repair, cell cycle progression, and maintenance of genomic integrity, the precise function of the BRCA1 gene as a tumor suppressor is still not clear." (PMID 25426449, 2014). "All these responsibilities of BRCA1 may collectively participate in tumor suppression; however, precise mechanisms of how the BRCA1 protein functions as a tumor suppressor are still not yet fully understood." (PMID 24704793, 2014). "A mutation of S1598F in BRCT domain that ablates phosphoprotein recognition was also found to be defective in the control of genome integrity and this mutant Brca1 failed to function as a tumor suppressor in three separate mouse models of Brca1-dependent tumorigenesis." (PMID 24704793, 2014). "Such a dualistic role might explain the bewildering lack of consistency of the LOH studies in BRCA1-related tumours to date." (PMID 24950059, 2014). "Tumor cells lacking BRCA1 and BRCA2 are sensitive to PARP inhibitors." (PMID 24784564, 2014). "We can speculate that in the presence of high BRCA1 expression, which confers high capacity for homologous recombination – and consequently, greater tumor resistance to platinum therapy – 53BP1 might not be essential for determining platinum sensitivity." (PMID 24197907, 2013). "However, although there are limited data (n = 22), an association between BRCA1/2 loss and activation of the PIK3CA/mTOR pathway in human tumours has not been confirmed." (PMID 23971979, 2013). "It must be considered that although triple negativity is enriched in BRCA1 mutant profiles, not all BRCA1 tumours may possess a triple negative phenotype." (PMID 23863842, 2013). "We would therefore predict that MMe tumours lacking expression of BRCA1 might also represent a molecularly defined subgroup of tumours with sensitivity to PARP1 inhibition." (PMID 23301673, 2013). "Interestingly, the well-known tumour suppressor and DSB repair protein BRCA1, whose optimal relocalisation to subnuclear foci at DNA lesions requires MDC1 (in the presence of DSBs) and a proficient FANC pathway (in response to ICLs), was recently shown to be involved in the response of cells to UVC." (PMID 23365640, 2013).
tumor (continued). "The authors suggested that the tumor causing mutations in the RING domain of BRCA1 are the missense mutations that abolish BRCA1-BARD1 heterodimerization and not the ones that abolish the E3 ligase activity of BRCA1." (PMID 24832651, 2013). "A recent study of mice carrying a BRCT mutant of BRCA1 that is defective in recognition of phosphorylated proteins and mice carrying an E3 ligase defective mutant of BRCA1 indicates that BRCT phosphoprotein recognition but not the E3 ligase activity is required for BRCA1 tumor suppression." (PMID 22369660, 2012). "In NSCLC, chemotherapeutic treatment can damage DNA through various mechanisms, the lack of functional BRCA1 can lead to increased sensitivity of the tumor cells to molecular damage, demonstrating that BRCA1 represents a predictive marker of chemotherapy response in NSCLC." (PMID 22439756, 2012). "Interestingly, multiple other potential functions have been proposed for the BRCA1 and BRCA2 proteins that may have an impact on their tumor suppressor function." (PMID 22737296, 2012). "Given that Capan-1 is a BRCA2 deficient model, we investigated the possibility that medium depth, whole genome sequencing could be used to distinguish BRCA1 and BRCA2 deficient tumours from non-familial forms." (PMID 21750719, 2011). "The apparent differences in SNP associations between BRCA1 and BRCA2 carriers, and non-carriers, may be explicable by differences in the prevalence of tumour subtypes." (PMID 22053997, 2011). "Our results show that incorporating tumour marker information into BOADICEA may result in the better discrimination between BRCA1 carriers, BRCA2 carriers and nonmutation carriers." (PMID 20482762, 2010). "Indeed, in the early response to UV and MMS, but not to IR, dispersion of BRCA1/BARD1 from nuclear foci is accompanied by ubiquitin-mediated degradation of both tumor suppressors." (PMID 21103343, 2010). "We also show that BRCA1 downregulation (i) is not cell-type specific, as it occurs in various tumor cell lines and moreover (ii) was observed in primary human fibroblasts, revealing that the downregulation is not specific to transformed or tumor-derived cells." (PMID 21103343, 2010). "Somatic mutations in BRCA1 and BRCA2 have not been found and the involvement of these genes in sporadic tumour development therefore remains unclear." (PMID 19589159, 2009). "Tumor cells lacking BRCA1 or BRCA2 function are highly genetically unstable." (PMID 19825178, 2009). "Although the BRCA1 status of our patient has not been identified, it was suggested the possibility that the tumor cells of our MPC might be blocked differentiation with expansion of undifferentiated cell compartment." (PMID 18559079, 2008). "Conversely, the detection level of the AI analysis was limited by the fact that none of the tumours were micro/macrodissected prior to DNA isolation, which also means that unmethylated BRCA1 alelles are always detected in the tumour samples due to the presence of normal DNA." (PMID 16846527, 2006). "Indeed, all but one of the BRCA1 methylated tumours that had absent/markedly reduced BRCA1 protein expression (8 of 9) also had a detectable deletion of the BRCA1 gene." (PMID 16846527, 2006). "However, our results with a mutant BRCA1 protein showed that despite an intact amino terminus, the truncated tumor suppressor was not able to inhibit E2-mediated increases in double-strand break repair and cell survival." (PMID 16417649, 2006).
tumor (continued). "As both the BRCA1 and BRCA2 proteins are involved in postreplicative DNA repair, reducing the proliferative activity of the breast luminal epithelial cell population from which most tumours are derived should reduce the number of opportunities for replication errors to occur." (PMID 16538216, 2006). "The four BRCA1 methylated tumours that did not exhibit significantly reduced BRCA1 expression could possibly be heterogenous with respect to this alteration." (PMID 16846527, 2006). "However, to date there is no consistent evidence that BRCA1/2-mutant tumours carry a higher likelihood of radiocurability, but this is in large part due to the fact that residual tumour burden is the critical determinant of local control." (PMID 15054444, 2004). "For all families, where an affected individual has been found not to carry the BRCA1 or BRCA2 mutation, that tumour has not been included in the calculations and, of course, only tumours occurring in blood relatives of mutation-positive family members are counted." (PMID 12698193, 2003). "In addition, in our unselected cohort, many PGVs are identified in genes such as BRCA1, MSH6, PMS2, and NF1, which are crucial not only for germline follow-up but also for selecting appropriate therapies, particularly immune-based or targeted treatments, as observed in other tumor types." (PMID 41168197, 2025). "Remarkably, pathogenic variants in BRCA1/2 were present in patients both with and without clinical benefit, whereas variants in other known homologous recombination repair (HRR) genes were identified exclusively in tumor samples from patients with clinical benefit (ABRAXAS1, FANCA, and RAD51C)." (PMID 39591206, 2024). "Notably, in the five tumours with detected SBS3 (OESO_0113, OESO_0040, OESO_0125, OESO_0025 and OESO_0008), only private mutations were assigned to the BRCA signature (SBS3), but no non-synonymous mutations in BRCA1/2 were found." (PMID 39020404, 2024). "Because p18−/− luminal tumor cells did not generate tumors when they were transplanted into MFPs without exogenous estrogen, we were unable to determine and compare the effect of estrogen in inducing DNA damage in p18−/− (Gata3+/+;Brca1+/+) luminal type tumorigenesis." (PMID 38627785, 2024). "Afterwards, sensitivity to PARPi has been proved in tumor with loss of other tumor suppressor DNA repair proteins (e.g., ATR, ATM, RAD51, CHEK1/2, and PALB2), suggesting the validity of this therapeutic strategy also in patients intrinsically deficient in HR without BRCA1/2 mutations." (PMID 36793600, 2023). "Hence, if the functional importance of BRCA1_circRNA_3-2 could be speculated because BRCA1 exon 2 contains the wild-type translation initiation sequence, a putative functional mechanism for BRCA2 circRNA_26-13, which nearly disappears from tumor samples, remains unknown." (PMID 37046838, 2023).